ENSG00000274121
Gene: Miscellaneous RNA gene on chromosome 1 (231,814,982 to 231,815,186, forward strand). Ensembl gene ENSG00000274121.
Gene Ontology:
Biological process: regulation of gene expression